CDK4 (cyclin dependent kinase 4)
Diseases named in the same sentence as CDK4 in open-access papers (continued):
Sharing a sentence is not in itself a finding about the gene and the disease.
breast cancer (continued). "Additionally, BTX‐9341 targets CDK4/6, currently in Phase I trials in breast cancer patients (NCT06515470), while CG001419, as an NTRK‐targeting drug specifically for treating advanced solid tumors carrying NTRK alterations, is in Phase I/II clinical studies (NCT06636500)." (PMID 41049269, 2025). "Furthermore, a subset of ER+ breast cancers with defects in MutL mismatch repair and DNA damage repair exhibit resistance to all classes of endocrine therapy, yet preclinical data indicate that such tumors still respond to CDK4/6i." (PMID 41226361, 2025). "In recent years, a range of cyclin-dependent kinase 4/6 (CDK4/6) inhibitors have been identified as significantly improving the survival of patients with hormone receptor-positive (HR+)/human epidermal growth factor receptor 2-negative (HER2-) breast cancer (BC)." (PMID 40620712, 2025). "Additionally, ATRT cell lines showed a similar sensitivity to abemaciclib in colony formation assays as MCF7 cells, an ER+ breast cancer line known to be highly susceptible to CDK4/6 inhibition, whereas other non-ATRT solid tumors showed substantially lower sensitivity to CDK4/6 inhibition." (PMID 39617889, 2024). "Hence, we propose that the combination of ER and PRMT5 inhibitors can synergistically block the G1-to-S transition in ER+/RB-deficient breast cancer, independent of the CDK4/6/Cyclin D1 complex." (PMID 38480701, 2024). "However, the role of CDK4/6 inhibitors in early breast cancer remains controversial." (PMID 39329126, 2024). "Therefore, this meta-analysis included all available randomized controlled trials (RCTs) aimed at exploring the efficacy and safety of CDK4/6 inhibitors combined with endocrine therapy in the adjuvant or neoadjuvant treatment of patients with HR-positive/HER2-negative early breast cancer." (PMID 39329126, 2024). "In breast cancer tumours and cell lines, we have reported that the highly variable abundance of phospho‐CDK4 signals the presence or absence of active CDK4 targeted by CDK4/6i, which was associated with the sensitivity or insensitivity of tumour cells to palbociclib." (PMID 36453028, 2024). "Therefore, inhibition of CDK4 activity has become an important strategy for treating breast cancer." (PMID 38215156, 2024). "Notably, the administered neratinib dose considerably deviated from current clinical standards, providing an innovative perspective on a potent, well-tolerated, and enhanced treatment strategy for HR+/HER2-low breast cancer, extending beyond CDK4/6 inhibitors combined with endocrine therapy." (PMID 39730704, 2024). "Furthermore, CCNE1 expression has been suggested to be a predictive biomarker, with high CCNE1 RNA expression correlating with decreased progression-free survival in patients with metastatic hormone receptor–positive, HER2-negative breast cancer receiving the CDK4/6 inhibitor Palbociclib." (PMID 38717153, 2024). "Given our observation that CDK4/6-resistant breast cancer cells are markedly sensitive to the addition of INX-315 (IC50 <25 nmol/L), it is plausible that these combinations might be effective using low doses of selective CDK2 inhibitors, thereby improving the overall tolerability profile." (PMID 38047585, 2024). "Since adjuvant CDK4/6 inhibitors (eg, abemaciclib) improve survival of luminal breast cancer at high risk, without ALND makes revealing four or more lymph nodes metastases impossible, which results in these patients not meeting the criteria of adjuvant CDK4/6 inhibitors therapy." (PMID 39544961, 2024). "Thus, it is suggested that CFI-402257 administration could be beneficial to ER+ breast cancer patients resistant to CDK4/6-targeting therapies." (PMID 39339232, 2024). "Additionally, this work investigated whether neratinib could reverse this effect, thereby exploring enhanced therapeutic options involving CDK4/6 inhibitors for HR+/HER2-low breast cancer." (PMID 39730704, 2024).
breast cancer (continued). "Thus, dysregulation of IFN signaling leads to resistance to CDK4/6is in breast cancer cell lines." (PMID 39593745, 2024). "Notably, the clinical approval of inhibitors targeting CDK4/6, whose activity is determined by cyclin D1 protein level, highlights the pronounced clinical significance of cyclin D1 in the context of cancer therapeutics, particularly for breast cancer." (PMID 38551001, 2024). "The results revealed that abemaciclib, the first CDK4/6 inhibitor used in combination with endocrine therapy, can significantly enhance the invasive disease-free survival (IDFS) in patients with node-positive HR+/HER2-breast cancer who are at a high risk of early recurrence." (PMID 38327984, 2024). "Finally, we used two CDK4/6 inhibitors, LY2835219 (Abemaciclib) and PD0332991 (Palbociclib), both of which are used in breast cancer patients, to see whether inhibition of CDK4/6 would reproduce the effects of calcium/ionomycin on TFEB activity." (PMID 38212474, 2024). "Besides, the treatment of C3I-22 could overcome the acquired drug resistance to CDK4/6 inhibitor in ER+ breast cancer." (PMID 38963708, 2024). "Also, [18F]NT431 may have potential application in peripheral tumors such as breast cancer and other CDK4/6 positive tumors." (PMID 38999983, 2024). "The clinical relevance of RET expression in ER+ breast cancer was investigated by gene array analysis of primary tumors treated with endocrine therapy and by immunohistochemical scoring of metastatic lesions from patients who received combined CDK4/6i and endocrine therapy." (PMID 39931212, 2024). "Thus, CPVL knockdown reduced breast cancer cell resistance to CDK4/6 inhibitors in vivo." (PMID 36825764, 2023). "Hence, we propose that the combination of ER and PRMT5 inhibitors can synergistically block the G1-to-S transition in ER+/RB-deficient breast cancer, and this effect is independent of the CDK4/6/Cyclin D1 complex." (PMID 37502925, 2023). "Whether PARP1 drives CDK4/6i resistance in breast cancer is worth further study." (PMID 38037159, 2023). "Several investigations have shown that CDK4 is overexpressed in cancer and inhibiting CDK4 overexpression improves clinical treatment efficacy for breast cancer, melanoma, liposarcoma, and mantle cell lymphoma, which suggests that CDK4 could be a therapeutic target for cancer." (PMID 37894904, 2023). "CPVL might be a key factor in regulating breast cancer resistance to CDK4/6 inhibitors." (PMID 36825764, 2023). "Thus, a program of cellular senescence may negatively influence the sensitivity of HR+ breast cancer to RT combined with CDK4/6 inhibitors, a possibility that awaits validation in other experimental systems." (PMID 36765430, 2023). "Additionally, CDK4/6 is disordered in numerous cancers, such as breast cancer, osteosarcoma, and acute megakaryoblastic leukemia." (PMID 37234717, 2023). "Thus, achieving significant improvements in survival rates in the advanced and early breast cancer treatment setting, CDK4/6 inhibitors are the first substances in almost two decades to substantially change the standard of care for advanced breast cancer patients." (PMID 36980649, 2023). "Additionally, progesterone receptor B signaling could negatively regulate breast cancer cell migration and metastasis by affecting the Cyclin-D1/Cdk4/Paxillin interaction and Paxillin phosphorylation." (PMID 36869991, 2023). "Given the reported similarities between PH and cancer, and the efficacy of CDK4/6 inhibitors in the treatment of breast cancer, we sought to identify whether a similar oxidant-induced inhibition was observed in the proliferation of MCF7 breast epithelial cells." (PMID 37955182, 2023). "Therefore, from the therapeutic perspective, PEG10 could be a potential therapeutic target for CDK4/6 inhibitor-resistant breast cancer." (PMID 38017459, 2023). "The tumor suppressor FAT1 may mediate CDK4/6i resistance in ER + breast cancer." (PMID 38037159, 2023).
breast cancer (continued). "Besides, bi-steric mTORi RMC-6272-mediated inhibition of mTORC1 in ER + /HER2- breast cancer has displayed significant efficacy in hormone therapy-resistant acquired patient-derived xenografts, and in patient-derived xenografts from CDK4/6 inhibitor-resistant patients." (PMID 37596643, 2023). "Despite the fact that CDK4/6 alterations are very common in many types of malignancies and that numerous preclinical studies on these agents have shown tumor suppressive effect, significant clinical benefits have only been demonstrated primarily in breast cancer and to a lesser extent, WDLPS/DDLPS." (PMID 37298520, 2023). "•Cyclin-dependent kinase 4/6 (CDK4/6) inhibitors have changed the treatment of hormone-sensitive breast cancer (BC)." (PMID 37198053, 2023). "In the population of breast cancer patients who undergo radiotherapy for brain metastases (n = 14) (excluding those with bone and meningeal metastases only), at the time of data cut-off, ten patients had PD, three continued CDK4/6i treatment, and one was lost to follow-up." (PMID 36902831, 2023). "In addition, abemaciclib and palbociclib treatment have been shown to downregulate mTOR signaling in small cell lung and breast cancer, providing support that CDK4/6 inhibitors may induce reversible senescence through downregulating mTOR signaling." (PMID 37035239, 2023). "With the introduction of effective palliative systemic treatments, e.g., CDK4/6-inhibitors in breast cancer, and enzalutamide and abiraterone in prostate cancer, pts with bone metastases originating from these malignancies may have a life expectancy of several years." (PMID 38136282, 2023). "Furthermore, less than 50% of patients with HR+, HER2− advanced breast cancer are prescribed CDK4/6 inhibitors as first‐line treatment despite approvals in the first‐line setting, illustrating the continued relevance of the SANDPIPER population to a real‐world setting." (PMID 36892268, 2023). "Recently, it was demonstrated that in a real-world population of HR+/HER2− advanced breast cancer patients receiving CDK4/6i plus ET in the first line, the proliferative index marker Ki67 was significantly inversely correlated with PFS, suggesting that this may be a marker of CDK4/6i resistance." (PMID 35860587, 2022). "Interestingly, loss of CDK4 expression does not affect the onset or incidence of mammary tumors that result from WNT-1 expression." (PMID 36051751, 2022). "CDK4/6 inhibitors are currently only approved to treat ER+ breast cancers, but our data build on a growing body of evidence that suggest there may be clinical relevance in expanding the use of CDK4/6i in combination with DNA damaging or cytotoxic agents to treat TNBC and other cancer types." (PMID 34932500, 2022). "Interestingly, the activin-SMAD pathway, a downstream target of CDK4/6 (independent of Rb) was shown to be a good target for palbociclib in CREB3L1-deficient T47D luminal A breast cancer cells." (PMID 36123435, 2022). "However, given that CDK4/6 inhibitors combined with endocrine treatment improved both progression-free survival and overall survival and had a good toxicity profile, CDK4/6 inhibitors are considered the preferred option in ER+ gBRCA breast cancer." (PMID 35805038, 2022). "The palbociclib-resistant preclinical model developed in the current study investigated whether the combination of abemaciclib, CDK4/6 inhibitor with eribulin, an antimitotic chemotherapy could be a strategy to overcome palbociclib-resistant HR-positive breast cancer." (PMID 35008374, 2022). "Previous studies combining low doses of CDK4/6i with RT demonstrate clinically meaningful radiosensitization in ER+ breast cancer models, though others have since suggested that combination treatment may be most effective when RT is administered prior to CDK4/6 inhibitor therapy." (PMID 34932500, 2022).
breast cancer (continued). "In addition, a variety of treatments are still in clinical trials, including IL-8/CXCR inhibitors, breast cancer vaccines, and lysing viruses, angiogenesis inhibitors, and inhibitors of cyclin-dependent kinase 4 (CDK4) and CDK6, in combination with PD-1/PD-L1 inhibitors." (PMID 36012144, 2022). "Thus far, clinical trials using CDK4/6 inhibitors have been mostly restricted to women with ER+HER2– breast cancer, and their potential role in treating TNBC remains unclear." (PMID 34932500, 2022). "Also, CCL5 was found to be increased, and chemokine/chemokine receptor signature was enriched after CDK4/6 inhibitor treatment in a phase II study in HR+/HER2− breast cancer patients and in a mouse model of mammary tumors, which are in agreement with our findings." (PMID 37181790, 2022). "As mentioned, one concern with the use of CDK4/6 inhibitors is the development of resistance mechanisms to these therapies through quasi-redundant or alternative signaling pathways, which has been reported in breast cancer and medulloblastoma patients receiving CDK inhibitor monotherapy." (PMID 35936751, 2022). "Interestingly, a PI3K inhibitor-based combination drug screening conducted on PIK3CA mutant breast cancer revealed that combined CDK4/6-PI3K inhibition could overcome intrinsic and acquired resistance of PI3K inhibitors and lead to tumor regressions." (PMID 35546399, 2022). "Among the mutations identified in the test that may be associated with RMS, the CDK4 gene (Case 1) was located at 12q14, encoding the cell cycle regulator CDK4, and its amplification was observed in ARMS, breast cancer, non-small cell lung cancer, and glioblastoma multiforme." (PMID 36686750, 2022). "The discovery that dysregulation of the CDK4/6 pathway is involved in breast cancer (BC) cell proliferation has led to the development of selective CDK4/6 inhibitors, which have dramatically changed the management of breast cancer (BC) patients in advanced settings." (PMID 36498861, 2022). "Therefore, targeting CDK4/6 is a very reasonable strategy in HER2+/HR+ breast cancer." (PMID 34977029, 2021). "In addition, based on preclinical studies suggesting that activation mutations or amplification of the FGFR pathway cause acquired resistance to CDK4/6 inhibitors, the FGFR tyrosine kinase inhibitor lucitanib has been clinically tested in patients with advanced breast cancer." (PMID 32860163, 2021). "Since this trial participants are by eligibility criteria breast cancer patients with an indication to CDK4/6 inhibitors in clinical practice, the comparison between the rate of accrual pre‐ and post‐March 2020 may be intended as a proxy of this specific treatment assignment in course of lockdown." (PMID 33677841, 2021). "The recent TRINITI-1 trial (NCT02732119) differs from the others that have explored the use of mTOR inhibitors in ER+ breast cancer patients because patients in this trial were actually treated with ribociclib as part of their regimen even though they had previously progressed on a CDK4/6 inhibitor." (PMID 34830174, 2021). "Consequently, targeting CDK4/6 in ER+ breast cancers is an effective therapeutic strategy." (PMID 34830174, 2021). "Moreover, knocking-down of βTrCP1 suppressed HFF1 cell proliferation, in which RB1 proteins were mainly in hypophosphorylated form and supposed to have higher affinity with βTrCP1, and enhanced the inhibitory effect of CDK4/6i on MCF7 breast cancer cell proliferation." (PMID 34508104, 2021). "Notably, among those genetic alteration events whose loss enhances CDK4/6i sensitivity, CDK6, CCND3, CCNE1 and E2F3 were frequently amplified in the genomes of breast cancer patients, whereas among the genes whose loss promotes resistance, RB1, REXO2, PPP2R2A and STT3A were mainly depleted." (PMID 34508104, 2021).
breast cancer (continued). "Importantly, it was previously shown that breast cancer cells resistant to CDK4/6 inhibitors can be successfully eradicated using drugs that target the downstream signalling of the receptor tyrosine kinases, such as lucitanib (FGFR) and alpelisib (p110α-selective inhibitors of PI3K)." (PMID 34944934, 2021). "In addition, targeted proteins for breast cancer therapy are also CDK4, CDK6, PARP, PI3K and RAL." (PMID 34361688, 2021). "In this prospective study, we demonstrate proof‐of‐concept that longitudinal z‐score trajectories rather than single time point measurements may harbor important dynamic information on the development of disease progression in HR+HER2− breast cancer patients undergoing CDK4/6 inhibitor treatment." (PMID 33264486, 2021). "Palbociclib was the first CDK4/6 inhibitor to receive US Food and Drug Association (FDA) approval in postmenopausal hormone receptor-positive HR (+), epidermal growth factor receptor 2-negative HER (−) advanced breast cancer, based on the results of the PALOMA-2 Phase III trial." (PMID 34439268, 2021). "In conclusion, this proof‐of‐concept study is the first to demonstrate that longitudinal assessment of tumor fractions using untargeted mFAST‐SeqS as a surrogate may harbor important prognostic information on disease progression in HR+/HER2− breast cancer patients undergoing CDK4/6 treatment." (PMID 33264486, 2021). "Interestingly, it has been also demonstrated that the cyclin D/CDK4 complex might regulate PD-L1 protein abundance, leading to its proteasomal degradation and that CDK4/6i increases PD-L1 levels in vivo, in breast cancer models." (PMID 34204543, 2021). "A combination of autophagy inhibitor HCQ, CDK4/6 inhibitor Palbociclib, and the immune checkpoint programmed cell death-1 (PD-1)/Programmed death-ligand 1 (PD-L1) inhibitor avelumab to eradicate dormant breast cancer has entered a phase II clinical trial (NCT04841148)." (PMID 34685686, 2021). "Interestingly, we found that higher CDK2 and CDK4 expressions were associated with non-responsiveness of breast cancer patients to therapy." (PMID 34421361, 2021). "However, the clinical scenario could be much more complex according to potential drug-drug interactions (DDIs) in patients with breast cancer treated with CDK4/6 inhibitors; DDIs may occur in patients who take polypharmacy." (PMID 33477469, 2021). "Among women, the most common type of breast cancer is the hormone receptor-positive/human epidermal growth factor receptor 2 negative (HR+/HER2−-) breast cancer, where CCND1 as an encoding of cyclin D1, the catalytic subunit of CDK4 and CDK6, is profoundly expressed." (PMID 34948218, 2021). "Additionally, in search of other possible pathways that could be responsible for the development of resistance to CDK4/6 inhibitor, we analyzed genomics and transcriptomics of palbociclib-sensitive and resistant breast cancer cells." (PMID 33504001, 2021). "With the majority of patients with advanced ER+ breast cancer expected to receive CDK4/6i as part of their treatment, and the high likelihood of the development of resistance to CDK4/6i in a given patient, the post CDK4/6i treated phenotypes represent new biological states for ER+ breast cancer." (PMID 34804982, 2021). "Therefore, AZD1775 is effective as a single agent in ER+ breast cancer cells that are resistant to antiestrogen and CDK4/6 inhibitors but the anti-proliferative effect of WEE1 inhibition in these cells is hampered when combined with antiestrogens or CDK4/6 inhibitors." (PMID 34277427, 2021). "FDG and FLT-PET are promising to detect changes in tumor biology early, prior to shrinkage of tumor, and could be used to measure the impact of CDK4/6 inhibitors, increasingly used with endocrine therapy in ER+ breast cancer, or other molecularly targeted agents." (PMID 34425871, 2021).